STAT1 (signal transducer and activator of transcription 1)
Description:
Signal transducer and transcription activator that mediates cellular responses to interferons (IFNs), cytokine KITLG/SCF and other cytokines and other growth factors. Following type I IFN (IFN-alpha and IFN-beta) binding to cell surface receptors, signaling via protein kinases leads to activation of Jak kinases (TYK2 and JAK1) and to tyrosine phosphorylation of STAT1 and STAT2. The phosphorylated STATs dimerize and associate with ISGF3G/IRF-9 to form a complex termed ISGF3 transcription factor, that enters the nucleus. ISGF3 binds to the IFN stimulated response element (ISRE) to activate the transcription of IFN-stimulated genes (ISG), which drive the cell in an antiviral state. In response to type II IFN (IFN-gamma), STAT1 is tyrosine- and serine-phosphorylated. It then forms a homodimer termed IFN-gamma-activated factor (GAF), migrates into the nucleus and binds to the IFN gamma activated sequence (GAS) to drive the expression of the target genes, inducing a cellular antiviral state. Becomes activated in response to KITLG/SCF and KIT signaling. May mediate cellular responses to activated FGFR1, FGFR2, FGFR3 and FGFR4. Following bacterial lipopolysaccharide (LPS)-induced TLR4 endocytosis, phosphorylated at Thr-749 by IKBKB which promotes binding of STAT1 to the 5'-TTTGAGGC-3' sequence in the ARID5A promoter, resulting in transcriptional activation of ARID5A and subsequent ARID5A-mediated stabilization of IL6. Phosphorylation at Thr-749 also promotes binding of STAT1 to the 5'-TTTGAGTC-3' sequence in the IL12B promoter and activation of IL12B transcription. Involved in food tolerance in small intestine: associates with the Gasdermin-D, p13 cleavage product (13 kDa GSDMD) and promotes transcription of CIITA, inducing type 1 regulatory T (Tr1) cells in upper small intestine (By similarity).
Synonyms: STAT91; ISGF-3; CANDF7; IMD31A; IMD31B; IMD31C
Tractability: Small molecule: a high-quality ligand is known; it belongs to a druggable protein family. PROTAC: UniProt records ubiquitination sites on it; ubiquitination databases record sites on it; its protein half-life has been measured; a small molecule that binds it is known.
Target class: Transcription factor
Gene: Protein-coding gene on chromosome 2 (190,908,460 to 191,020,960, reverse strand). Ensembl gene ENSG00000115415.
Subcellular location: Cytoplasm; Nucleus
Subcellular location (Human Protein Atlas): Cytosol; Nucleoplasm
Pathways (Reactome):
Immune System: Growth hormone receptor signaling; ISG15 antiviral mechanism; Inactivation of CSF3 (G-CSF) signaling; Interferon alpha/beta signaling; Interferon gamma signaling; Interleukin-20 family signaling; Interleukin-21 signaling; Interleukin-27 signaling; Interleukin-35 Signalling; Interleukin-4 and Interleukin-13 signaling; Interleukin-6 signaling; Interleukin-9 signaling; PKR-mediated signaling; Regulation of IFNA/IFNB signaling; Regulation of IFNG signaling; Regulation of PD-L1(CD274) transcription; Signaling by CSF1 (M-CSF) in myeloid cells; Signaling by CSF3 (G-CSF)
Disease: SARS-CoV-2 activates/modulates innate and adaptive immune responses; Signaling by ALK fusions and activated point mutants; Signaling by PDGFRA extracellular domain mutants; Signaling by PDGFRA transmembrane, juxtamembrane and kinase domain mutants; Signaling by cytosolic FGFR1 fusion mutants; Signaling by phosphorylated juxtamembrane, extracellular and kinase domain KIT mutants
Signal Transduction: Downregulation of SMAD2/3:SMAD4 transcriptional activity; Downstream signal transduction; NOTCH3 Intracellular Domain Regulates Transcription; Signaling by SCF-KIT
Cellular responses to stimuli: Turbulent (oscillatory, disturbed) flow shear stress activates signaling by PIEZO1 and integrins in endothelial cells
Developmental Biology: Differentiation of naive CD4+ T cells to T helper 1 cells (Th1 cells)
Gene expression (Transcription): Regulation of RUNX2 expression and activity
Gene Ontology:
Molecular function: cadherin binding; DNA-binding transcription factor activity; DNA-binding transcription factor activity, RNA polymerase II-specific; double-stranded DNA binding; enzyme binding; histone acetyltransferase binding; histone binding; identical protein binding; promoter-specific chromatin binding; protein binding; protein homodimerization activity; RNA polymerase II cis-regulatory region sequence-specific DNA binding; RNA polymerase II core promoter sequence-specific DNA binding; RNA polymerase II transcription regulatory region sequence-specific DNA binding; transcription coactivator binding; transcription corepressor binding; tumor necrosis factor receptor binding; ubiquitin-like protein ligase binding; DNA binding
Biological process: cell surface receptor signaling pathway via JAK-STAT; cell surface receptor signaling pathway via STAT; cellular response to interferon-beta; cellular response to type II interferon; defense response to virus; endothelial cell migration; interleukin-27-mediated signaling pathway; interleukin-7-mediated signaling pathway; interleukin-9-mediated signaling pathway; negative regulation by virus of viral protein levels in host cell; negative regulation of angiogenesis; negative regulation of canonical NF-kappaB signal transduction; negative regulation of endothelial cell proliferation; positive regulation of defense response to virus by host; positive regulation of DNA-templated transcription; positive regulation of erythrocyte differentiation; positive regulation of interferon-alpha production; positive regulation of transcription by RNA polymerase II; regulation of transcription by RNA polymerase II; renal tubule development; response to interferon-beta; response to type II interferon; tumor necrosis factor-mediated signaling pathway; type I interferon-mediated signaling pathway; type II interferon-mediated signaling pathway; and 12 more
Cellular component: chromatin; cytoplasm; cytosol; ISGF3 complex; nucleoplasm; nucleus; perinuclear region of cytoplasm; protein-containing complex; RNA polymerase II transcription regulator complex
Genetic constraint (gnomAD): Loss-of-function variants: 20 observed, 107.39 expected, observed/expected ratio (o/e) 0.19, 90% interval 0.13 to 0.27. The upper end of that interval is the gene's LOEUF score, 0.27, which puts it in group 1 of 6, group 1 being the genes least tolerant of losing a copy. Missense variants: 337 observed, 921 expected, observed/expected ratio (o/e) 0.37, 90% interval 0.33 to 0.4. Synonymous variants: 318 observed, 333.55 expected, observed/expected ratio (o/e) 0.95, 90% interval 0.87 to 1.05.
Gene-disease validity (ClinGen):
ClinGen rates the evidence that STAT1 causes each of these diseases.
autoimmune enteropathy and endocrinopathy - susceptibility to chronic infections syndrome (autosomal dominant): Definitive.
immunodeficiency 31B (autosomal recessive): Definitive.
Homologues: Orthologues: chimpanzee STAT1 (99% identical), macaque STAT1 (99% identical), pig STAT1 (96% identical), dog STAT1 (96% identical), rabbit STAT1 (95% identical), mouse Stat1 (93% identical), guinea pig STAT1 (92% identical), rat Stat1 (86% identical), tropical clawed frog stat1 (80% identical), zebrafish stat1a (61% identical), zebrafish stat1b (56% identical), Caenorhabditis elegans sta-1 (23% identical), and 1 more. Paralogues in human: STAT4 (53% identical), STAT3 (52% identical), STAT2 (42% identical), STAT5B (28% identical), STAT5A (28% identical), STAT6 (25% identical).
Diseases named in the same sentence as STAT1 in open-access papers:
STAT1 is named in the same sentence as 704 diseases in open-access papers, as found by Europe PMC text mining. Sharing a sentence is not in itself a finding about the gene and the disease. The quoted sentences say what the papers report.
viral infection (354 papers, 2002 to 2026). "Patients with STAT1 mutations have complete blockage of the IFN/STAT1 pathway and are susceptible to fatal bacterial and viral infections." (PMID 40920886, 2025). "There is a consensus that upregulation of STAT1 activation confers antiviral properties, with STAT1 deficiency often increasing the susceptibility to death from viral infections." (PMID 38675812, 2024). "This is in contrast to AR complete and partial STAT1 deficiency, in which recurrent viral infections is a common feature in addition to susceptibility to intracellular bacteria." (PMID 39840042, 2024). "The search for drugs capable of targeting viral proteins implicated in both viral replication and IFN/STAT1 inhibition is important for the treatment of the most viral infections and for future viral pandemics." (PMID 39201692, 2024). "STAT1 is critical in this pathway as both STAT1 knockout animal models and patients with loss of function mutations fail to clear viral infections." (PMID 36826612, 2023). "STAT1 is a signal transducer and transcription activator that mediates immune responses to interferons in viral infections, and its deleterious variants have been reported underlying life-threatening COVID-19 pneumonia." (PMID 37931111, 2023). "This miR-432 is associated with the phosphorylation of STAT-1 and the immune-mediated inflammatory response during viral infection." (PMID 37242305, 2023). "As can be seen, too little STAT1 immunity (from biallelic or DN mutations) is associated with a susceptibility to mycobacterial and viral infections." (PMID 37140667, 2023). "Both STAT2- and STAT1-deficient mice are more vulnerable to viral infections, however, unsurprisingly, the effect is more pronounced for STAT1-deficient mice as they also cannot respond to type II interferons, reviewed by Meyts & Casanova." (PMID 37669278, 2023). "In contrast, HSCT is curable in patients with complete STAT1 deficiency, who need to be alerted to fatal viral infections and serious complications." (PMID 36339330, 2022). "Patients affected by this form of STAT1 mutation have a complete block of the IFN/STAT1 pathway and are affected by lethal intracellular bacterial and viral diseases." (PMID 35456913, 2022). "To simulate a patient highly susceptible to viral infections, we used Stat1-deficient (Stat1−/−) adult mice, which are largely devoid of type I, II and III interferon responses and consequently lack key defense mechanisms to combat pathogen challenges." (PMID 36190240, 2022). "Increase in STAT1, during viral infections, by type 1 IFN or IFNγ, have been associated with decreased STAT4 access to receptors." (PMID 36072585, 2022). "Not unexpectedly, most overexpressed genes were involved in interferon signaling pathways and susceptibility to viral infection, which are mainly the targets of STAT1." (PMID 33915751, 2021). "Fourteen patients with STAT1 LOF mutations suffered virus infections, which included EBV (50.0%), VZV (41.7%), HSV (41.7%), CMV (41.7%), HHV (33.3%), RSV (33.3%), adenovirus (25.0%), Molluscum contagiosum/warts (16.7%), and parvovirus (8.3%)." (PMID 33777053, 2021). "Studies using mice deficient for STAT1 have illuminated the central role that STAT1 plays in determining the outcome of viral infection." (PMID 32310998, 2020). "Mutating Lys511 and Lys652 of STAT1 significantly promoted ISG expression in response to viral infection." (PMID 32123171, 2020). "Consistent with HOIP upregulation, viral infection leads to an increase in linear ubiquitination of STAT1, which is associated with HOIP." (PMID 32123171, 2020). "Previous work using models of viral infection reported an association between type I IFNs and the transcription factor signal transducer and activator of transcription 1 (STAT1)." (PMID 32101732, 2020). "Like Tyk2-deficient mice, Stat1-deficient mice are highly susceptible to bacterial and viral infections." (PMID 31781102, 2019).
viral infection (continued). "Collectively, these data demonstrate that SFTSV likely blocks IFN-STAT1 signaling by two mechanisms, i.e., NSs sequestration of STAT1 in IBs and viral infection-caused decrease of STAT1 abundance." (PMID 31191546, 2019). "STAT1 is mainly involved in the response to IFNs, STAT1 deficiency can cause increased susceptibility to viral infection and disorders of intracellular pathogen infection regulation." (PMID 29562634, 2018). "As IFN stimulation caused much greater STAT1 phosphorylation than did viral infection, the same blot is shown with both high and low levels of exposure." (PMID 28228588, 2017). "STAT1-deficient mice exhibit heightened susceptibility to bacterial and viral infections, and human STAT1 deficiency results in an autosomal recessive immunological disease characterized by repeated bacterial and viral infections, indicating impaired NK cell activity (39, –, 42)." (PMID 40298450, 2025). "Diagnostic investigations include genetic testing for STAT1 variants, immunological profiling revealing low IL-17A-producing T cells, and comprehensive microbiological assessments to identify fungal, bacterial, and viral infections." (PMID 39859044, 2025). "Autosomal recessive (AR) complete STAT1 deficiency, reported in 24 patients from 15 kindreds, was described in 2003 as underlying severe viral infections due to impaired type I and III IFN signaling and of mycobacterial disease due to impaired type II IFN signaling." (PMID 36976641, 2023). "The reporting of more patients with rare diseases is essential to systematically identify sporadic complications (such as mycobacterial and viral infections in autosomal recessive complete STAT1 LOF mutations) and to apply them in the diagnosis of new patients." (PMID 37140667, 2023). "Also, other studies showed that STAT1 was essential in innate immunity and positively correlated with the susceptibility of viral infections." (PMID 36765396, 2023). "For example, STAT1-deficent mice are more susceptible to viral infection than wild-type mice." (PMID 35313878, 2022). "In contrast, the susceptibility to viral infections in AR deficiency could be explained by an impaired STAT1-dependent response to IFN-α/β." (PMID 36569938, 2022). "In humans, partial STAT1 deficiency leads to mycobacterial and viral diseases." (PMID 34653236, 2021). "Additionally, STAT1 has been largely associated with resistance against protozoan parasites and bacterial and viral infections." (PMID 34684235, 2021). "We previously observed an NSs-STAT1 colocalization but did not detect any STAT1 enrichment in the NSs immunoprecipitates of virus-infected cells (thus failing to unravel the direct targeting of STAT1 by NSs), which can be reasonably explained here by the STAT1 loss in the context of viral infection." (PMID 31191546, 2019). "This may explain why their susceptibility to viral infections is less severe when compared to patients harboring a STAT1-deficiency." (PMID 31781102, 2019). "Germline mutations that impair STAT1 function, by reducing either Tyr701 phosphorylation (L706S) or DNA binding (Q463H and E320Q), increase the susceptibility of otherwise healthy patients to mycobacterial and viral infection." (PMID 31408005, 2019). "However, when the first patient with AR STAT1 defect, with complete loss of STAT1 function, was identified, it turned out that this phenotype indeed does show increased susceptibility to a broad range of viral infections in addition to MSMD." (PMID 30671054, 2018). "Notably, the VSV infection-induced downregulation of NDR1 expression was abolished in IFNαR- or STAT1-deficient macrophages, thus indicating that viral infection inhibits NDR1 expression depending on STAT1 pathway." (PMID 30018336, 2018). "This speculation is further supported by the observation that mice lacking intact JAK/STAT signaling machinery (IFN receptor or STAT1 knockout mice) are highly susceptible to virus infection." (PMID 29662014, 2018).
viral infection (continued). "Recessive loss-of-function (LOF) mutations in STAT1 cause reduced signaling involving the STAT1 transcription factor, affecting immunity to intracellular pathogens primarily, like mycobacteria and viral infections due to impaired IFN-γ and IFN-α signaling, respectively." (PMID 29270166, 2017). "In humans, recessive loss-of-function mutations in STAT1 are associated with mycobacterial and viral infections, whereas gain-of-function (GOF) mutations in STAT1 are associated with a type of primary immunodeficiency related mainly, but not exclusively, to chronic mucocutaneous candidiasis (CMC)." (PMID 29270166, 2017). "Stat1-deficient mice are highly susceptible to bacterial and viral infections." (PMID 28149296, 2016). "Human subjects deficient in STAT1 die of bacterial and viral infections at an early age." (PMID 27687913, 2016). "Consequently, genetic loss of STAT1 function causes a marked susceptibility to viral infection in mice and humans." (PMID 22574190, 2012). "Our data also suggest that STAT1 may regulate the wound healing response following acute lung injury associated with viral infection, similar to its cell cycle regulation seen in other models of disease." (PMID 20386712, 2010). "Considering that STAT1 reflects more properly a mechanism linked to the induction of type I Interferon involved in the control of viral infection through the binding to the IFN-α type one receptor, it could be plausible to speculate about the role of these peptides to mimic a similar effect." (PMID 35408963, 2022). "Thus, in addition to giving the mechanistic explanation for SFTSV counteraction against IFN-γ, the present findings (particularly the virus infection-caused downregulation of STAT1 protein abundance) complement the knowledge of the viral antagonism strategies against type I and III IFNs as well." (PMID 31191546, 2019). "Similarly, STAT2-deficient mice exhibit reduced responsiveness to type I IFN and are more susceptible to viral infection, whereas STAT1-deficient mice are defective in their response to both type I and II IFNs and are highly sensitive to both viral and intracellular bacterial infections." (PMID 21379341, 2011). "Once inside the cells, it interacts with transcription factors and modulates the activity of genes like IFIT3 and STAT1 which are vital for responding to viral infections." (PMID 40936921, 2025). "We treated A549 cells with interferon (IFN) to determine the interferon-stimulated genes (ISGs) expression and STAT1 phosphorylation in the rg viral infection and plasmid transfection systems." (PMID 39972477, 2025). "We have observed that the effect of diminished STAT1 phosphorylation in the RIOK3-KO cells is most pronounced at the 24-h post virus infection." (PMID 40371100, 2025). "GOF variants in STAT1 (STAT1 GOF) lead to hyperactive STAT1 signaling, resulting in chronic mucocutaneous candidiasis and increased susceptibility to viral infections." (PMID 39859044, 2025). "Using an in vitro HBV infection assay system, the current study aimed to investigate the STAT1-independent host factors that contribute to the control of viral infection by comprehensive functional screening." (PMID 40048440, 2025). "Immunoblot analysis demonstrated that AGO2 deficiency significantly increased the phosphorylation of IRF3 and STAT1 upon virus infection." (PMID 40949099, 2025). "Generally, the antiproliferative effects of IFN-I are primarily mediated by STAT1, and IFN-I induced during viral infections can inhibit IFN-γ secretion in a STAT1-dependent manner." (PMID 41157628, 2025). "Collectively, these findings highlight mononuclear phagocytes as promising targets for future immunotherapies aimed at controlling pathological NF-kB- and STAT1-dependent immune responses and mitigating hyperinflammation in severe viral infections." (PMID 40934228, 2025). "STAT1 activation by oncogenic signaling or viral infection promotes tumor growth, survival, and angiogenesis." (PMID 41439111, 2025).